HMGB1 (high mobility group box 1)
Diseases named in the same sentence as HMGB1 in open-access papers (continued):
Sharing a sentence is not in itself a finding about the gene and the disease.
Stroke (continued). "Circulating HMGB1 concentrations were significantly elevated in individuals who developed cognitive dysfunction following stroke compared to those who maintained cognitive integrity (8.4 ± 1.2 ng/mL vs 4.6 ± 0.5 ng/mL, respectively; p < 0.001)." (PMID 38708343, 2024). "When a stroke injury occurs, HMGB1 enters the bloodstream to promote an inflammatory response and exacerbate brain injury." (PMID 39256844, 2024). "This ability to inhibit HMGB1’s pro-apoptotic effects extends beyond stroke, as demonstrated in TBI models, where GA mitigates brain edema and reduces the activation of microglia and astrocytes." (PMID 39598404, 2024). "The high-mobility group box 1 (HMGB1), which is stored in platelet α-granules and elevated in stroke patients, contributes to cerebral damage by promoting NET formation." (PMID 39334369, 2024). "The circulating HMGB1 was significantly lower in mice treated with lactadherin compared to mice treated with control 24 h after stroke." (PMID 38233928, 2024). "The levels of MPO-DNA, PAD4, C1q, IL-1β, IL-6, IL-8 and HMGB1 change significantly over time during the acute phase of stroke (all P < 0.05)." (PMID 39737165, 2024). "For detail, MPO-DNA, PAD4, C1q, IL-1β, IL-6 and IL-8 reached their peak at 24 hours after stroke onset and show a decreasing trend throughout the acute phase of stroke, while HMGB1 peaked at 48 hours after stroke onset." (PMID 39737165, 2024). "Among 192 patients with first-ever ischemic stroke, elevated HMGB1 levels early after stroke were an independent predictor of poorer cognitive performance on the Montreal Cognitive Assessment at 3-month follow-up." (PMID 38708343, 2024). "The results of this study indicate that HMGB1 could potentially serve as an innovative biological marker to pinpoint individuals who are more susceptible to experiencing cognitive deterioration following a stroke, and who might gain from timely therapeutic interventions." (PMID 38708343, 2024). "The systemic administration of the anti-HMGB1 monoclonal antibody (mAb) in animal models of stroke, brain trauma, and epilepsy significantly inhibited the translocation and release of HMGB1 from neurons, thus protecting the BBB from disruption." (PMID 38892076, 2024). "While our study lays the groundwork for the potential use of HMGB1 as a prognostic biomarker in stroke patients, further large-scale, multi-center studies and replication efforts are needed to confirm and extend our findings." (PMID 38708343, 2024). "To investigate the potential utility of circulating HMGB1 as a prognostic biomarker for post-stroke cognitive impairment (PSCI), we conducted multivariate logistic regression modeling adjusted for relevant covariates." (PMID 38708343, 2024). "Future research should focus on conducting randomized controlled trials to investigate the effect of interventions targeting HMGB1 on cognitive outcomes after stroke." (PMID 38708343, 2024). "Downregulation of SIRT6 has been shown to greatly enhance translocation of HMGB1 from the nucleus to the cytoplasm in stroke models in adult rats." (PMID 37787108, 2023). "In summary, we prepared ROS-responsive GA-conjugated DEAE-dextran nanoparticles (DGA) and demonstrated their neuroprotective ability by inhibiting HMGB1 and modulating microglia phenotypes to improve the therapeutic effect of stroke." (PMID 35415314, 2023). "Administration of anti-HMGB1 antibodies to the ischemic brain has been reported to inhibit NETs production, reduce neuronal death after stroke, and reduce subsequent neuroinflammation." (PMID 36892020, 2023). "Asthe HMGB1–RAGE interaction contributes importantly to stroke-inducedcerebral ischemic/reperfusion injury, blocking that interaction offersa pathway to reduce I/R injury." (PMID 37844138, 2023).
Stroke (continued). "Studies have shown that DAMPs, especially peroxiredoxin clearance in the brain by infiltrating mononuclear phagocytes, are beneficial for the resolution of sterile inflammation and treatment of stroke, where SR-A1 and HMGB1 are mentioned." (PMID 37143083, 2023). "After stroke, high mobility group box 1 (HMGB1) exacerbates brain cell injury by participating in the neuroinflammatory cascade and promoting microglia polarization to the M1 phenotype." (PMID 38370870, 2023). "A prior investigation revealed that circulating HMGB1 contents are generally upregulated by 10‐fold among stroke patients." (PMID 37132060, 2023). "Conversely, platelet-specific HMGB1 knockouts block platelet-induced NETs formation and improve stroke outcomes." (PMID 36892020, 2023). "Genes involved in key signaling processes after stroke, including Il-10, Il-12, Hmgb1, Il-13, p38 MAPK, HIF1α, Stat3, and Il-4, were inhibited by NPD1 + RvD1." (PMID 37270727, 2023). "Plasma levels of HMGB1 are increased in stroke and are even more elevated in the ischemic cerebral compartment in the acute phase of stroke." (PMID 35358095, 2022). "HMGB-1 levels were analyzed in association with every MACE composite outcome: cardiovascular death, myocardial infarction and stroke." (PMID 36244983, 2022). "HMGB1–RAGE signaling in stroke links macrophage activation with necrosis, providing a therapeutic target." (PMID 36421725, 2022). "Within the blood sample in stroke patients, serum markers of epinephrine and HMGB-1 were elevated compared to the control patients." (PMID 36338344, 2022). "As a common biomarker and potential target for traumatic brain injury (TBI), cerebral ischemia, stroke, epilepsy, and cognitive dysfunction, HMGB1 is involved in the neuroinflammation in these brain injury models." (PMID 36131309, 2022). "Studies have found that HMGB1 translocation is very sensitive to hypoxia, and it is released from the nucleus early in stroke to function as a pro-inflammatory factor." (PMID 36388178, 2022). "RAGE ligand high mobility group protein B1 (HMGB1) has been reported to be elevated in the serum of stroke patients, and RAGE receptors can act as sensors for the necrotic cell death, leading to inflammation and ischemic brain injury." (PMID 35281298, 2022). "HMGB1 can be altered by redox reactions with implications for acute and chronic cellular changes in stroke." (PMID 35203690, 2022). "In animal models of stroke, extracellular HMGB1 has been found to stimulate inflammation, albeit through TLR4 signaling instead of TLR2, as we showed here." (PMID 35573828, 2022). "HMGB1 unveils its second face during the late phase of the stroke involving brain tissue remodeling and repair." (PMID 36232519, 2022). "The high-mobility group box 1 (HMGB1) ligand released from necrotic cells seems to be the most obvious RAGE activator in stroke." (PMID 36421725, 2022). "In particular, the use of a monoclonal anti-HMGB1 Ab has been shown to be effective in treating central nervous system disorders such as stroke, traumatic brain injury, Parkinson’s disease, or Alzheimer’s disease." (PMID 35456925, 2022). "Twenty-four hours after stroke, thrombocytopenic mice had significantly lower levels of circulating HMGB1 compared with mice treated with an IgG control (5.9 ± 2 ng/mL vs. 9.5 ± 2.8 ng/mL, respectively)." (PMID 35358095, 2022). "These lines of evidence suggest that HMGB1 plays a dual role in stroke pathophysiology, the early being damaging, while the later on pro-resolving and facilitating the remodeling of the brain tissue." (PMID 36232519, 2022). "Subsequently, platelet-specific HMGB1-KO mice and their WT littermate controls were subjected to ischemic stroke, after which plasma was collected and stroke outcomes were analyzed." (PMID 35358095, 2022). "The use of the drug molecules proved to be efficacious in the prevention and acute treatment of stroke, reducing RAGE expression, thus inhibiting the HMGB1/RAGE axis in stroke conditions." (PMID 36364135, 2022).
Stroke (continued). "In a recent study, elevated levels of platelet–neutrophil aggregates along with elevated plasma and platelet surface-expressed HMGB1 levels were observed in stroke patients." (PMID 36430952, 2022). "Further, platelet-specific HMGB1-knockout mice not only had reduced NET formation after stroke induction but also improved stroke outcomes." (PMID 36430952, 2022). "HMGB1 levels were also higher in patients with severe strokes (NIHSS ≥17), indicating an important role of stroke severity and volume on the magnitude of systemic immune alteration long‐term after stroke." (PMID 35971650, 2022). "As a key promoter of neuroinflammation, HMGB1 is thought to be involved in the pathogenesis of Parkinson's disease, stroke, traumatic brain injury, epilepsy, autism, depression, multiple sclerosis, and amyotrophic lateral sclerosis." (PMID 36388178, 2022). "HMGB1 secreted by the astrocytes during the late phase of stroke promotes the function of the endothelial progenitor cells, which support the repair of the neurovascular unit and angiogenesis near the infarct territories." (PMID 36232519, 2022). "Platelets from stroke patients had significantly elevated HMGB1 surface expression and increased plasma HMGB1 levels compared with healthy donors." (PMID 35358095, 2022). "Twenty-four hours after stroke, HMGB1-KO mice had significantly lower plasma HMGB1 levels compared with WT mice (6.9 ± 3.1 ng/mL vs. 12.7 ± 3.6 ng/mL, respectively)." (PMID 35358095, 2022). "In a mouse model of cerebral ischemia, HMGB1 was found to be released from ischemic brain tissue and increased in the serum of stroke victims." (PMID 36421725, 2022). "HMGB1 is a well-characterized DAMP in the setting of stroke, where its in vivo neutralization results in decreased microglial activation, cytokine and iNOS expressions, and reduced permeability of the blood brain barrier." (PMID 34776788, 2021). "Blockade of HMGB1 with antagonists has been verified as an effective treatment strategy for animal stroke models, including GA, HMGB1 A box, and anti-HMGB1 monoclonal antibody." (PMID 34372857, 2021). "In a rat model of stroke, hyperglycemia enhanced release of HMGB1 and the rate of alteplase related HT." (PMID 34054705, 2021). "Various evidences demonstrate that Hmgb1 is released after cytokine stimulation and function as a pro-inflammatory cytokine in stroke." (PMID 34094642, 2021). "We next validated the roles of Hmgb2 in stroke damages.Hmgb2 is a member of high mobility group protein family (Hmgb1-Hmgb4) proteins that influence microglia pro-inflammatory response in some neurological disorders." (PMID 34094642, 2021). "Studies have gradually identified post-stroke DAMPs, such as high-mobility-group box 1 (HMGB1) and peroxiredoxins (Prxs)." (PMID 34162400, 2021). "This identification has fairly high credibility because HMGB1 is currently one of the crucial proinflammatory alarmins of stroke." (PMID 34372857, 2021). "Intensive studies of HMGB1, which is currently one of the crucial proinflammatory alarmins of stroke, in inflammation-related diseases have been performed for a number of years." (PMID 34372857, 2021). "In contrast to HMGB1 that is rapidly released during the hyperacute phase of brain ischemia (i.e., within 6 h after stroke onset), ischemic stress-induced Prxs are extracellularly released during the acute phase of ischemia (i.e., 12–24 h after stroke onset)." (PMID 34162400, 2021). "Other studies suggested that EE enhanced post-stroke angiogenesis via astrocytic HMGB1/IL-6 signaling pathway." (PMID 33841116, 2021). "As mentioned in the section on stroke, the plasma or CSF levels of HMGB1 increase significantly depending on the severity of brain injury." (PMID 33321691, 2020). "This review discusses NETosis and thrombosis and their crosstalk in various thrombosis-related diseases, focusing on the role of HMGB1 as a mediator in stroke." (PMID 32731558, 2020).
Stroke (continued). "Studies have shown that blood concentrations of HMGB1 are closely related to the severity and outcomes of stroke." (PMID 32410871, 2020). "Inhibition of the cytoplasmic translocation and release of HMGB1 serves as a strategy for stroke treatment." (PMID 32410871, 2020). "It was reported that HMGB1 upregulation promoted exogenous human peripheral blood-derived (hPB)-EPCs-mediated stroke recovery by modulating paracrine function of hPB-EPCs in transient MCAO mice." (PMID 33384585, 2020). "Our previous study showed that HMGB1 neutralization antibody treatment reduced neuronal injury in the peri-infarct regions of mice with stroke alone or stroke plus BF." (PMID 33187248, 2020). "The incidence of composite of morbidity endpoints (death, myocardial infarction, stroke, renal failure and prolonged ventilator care) was compared in relation to the tertile distribution of serum HMGB1 concentrations." (PMID 32286371, 2020). "Similar increases in HMGB1 in CSF or plasma have been observed in stroke patients with brain infarction, hemorrhage, and subarachnoid hemorrhage." (PMID 33321691, 2020). "Massive accumulations of HMGB1 in stroke patients and stroke animal models have been reported by many research groups including ours." (PMID 32731558, 2020). "The results of studies on IS suggest the important role of HMGB1 in stroke-induced immunosuppression, which is similar to a phenomenon observed in SAH." (PMID 31654316, 2020). "Inhibition of HMGB1 by siRNA 5 days post-stroke in vivo blocked the EPC response, reduced peri-infarct angiogenesis, and aggravated neurological deficits." (PMID 33384585, 2020). "A recent meta-analysis of 28 studies comprising almost 2700 IS patients found significantly increased circulating HMGB1 blood levels that were correlated with stroke severity and infarct volume." (PMID 31654316, 2020). "Increased levels of catecholamines and HMGB-1 post-stroke are a well-documented and were also reported by our group previously." (PMID 32581999, 2020). "In experiments using murine stroke models, elevated HMGB1 levels were detected in the brain tissue, serum, plasma and cerebrospinal fluid (CSF)." (PMID 32731558, 2020). "HMGB1 is a recognized pro-inflammatory factor for ischemic stroke and is positively correlated with the severity of stroke in animal models and patients." (PMID 33384585, 2020). "In a mouse model of focal cerebral ischemia, reactive astrocytes in the peri-infarct cortex upregulated HMGB1 on the fourteenth day after stroke, accompanied by the accumulation of endogenous endothelial progenitor cell (EPCs)." (PMID 33384585, 2020). "The release of HMGB1 is also related to the functional state of autophagy in the early stages of stroke." (PMID 31001089, 2019). "High-Mobility-Group-Protein B1 (HMGB-1) is elevated for at least 7 days post-stroke and has been suggested to mediate SIIA." (PMID 31118917, 2019). "High-mobility group box-1 (HMGB1) is a nuclear protein that promotes inflammation during the acute phase post-stroke, and enhances angiogenesis during the delayed phase." (PMID 31123914, 2019). "At the same time, increased numbers of HMGB1 positive microglia/macrophages are observed infiltrating the stroke area and exacerbating inflammation." (PMID 31001089, 2019). "HMGB-1 exposure also seems to induce pro-inflammatory priming in microglial cells of aged brains and the microglial inhibitor named minocicline reduces reactive microgliosis and HMGB-1 release by activated glia Stroke." (PMID 31507379, 2019). "In the early phase after brain injury and stroke, HMGB1 is passively secreted from damaged or necrotic cells and it is actively secreted from immune cells, inducing inflammation and necrosis." (PMID 31123914, 2019). "Several DAMP-s such as nucleic acids, ATP, S100 proteins, and HMGB1 have been found to contribute to the inflammatory response in stroke." (PMID 31291966, 2019).
Stroke (continued). "Recent evidence suggests that high-mobility group box 1 (HMGB1) protein can promote neuroinflammation after stroke in adult rodents, but its role in perinatal hypoxic-ischemic brain damage (HIBD) remains largely uninvestigated." (PMID 31920543, 2019). "It was suggested that at the early stage of stroke, HMGB1 is first passively released from the dying neurons, accompanied by active secretion by the actively infiltrated microglia/macrophages." (PMID 31001089, 2019). "Recent studies agree that HMGB1 is a recognized proinflammatory factor in ischemic stroke and positively correlates with stroke severity in animal models and patients." (PMID 31001089, 2019). "Post-stroke the amount of HMGB-1 correlates rather with the amount of leukocytes in the peripheral blood than with the brain lesion size." (PMID 31118917, 2019). "Fully reduced HMGB1 has been shown to be prevalent in the serum and brain samples of mice after 2 h of stroke." (PMID 31001089, 2019). "Real-time PCR and ELISA assays resulted in higher expression of TLR2 in monocytes of stroke patients stimulated with HMGB1." (PMID 31291966, 2019). "Others and we have reported earlier that HMGB-1 is elevated post-stroke at least for 7 days while its decoy receptors sRAGE and esRAGE are not altered." (PMID 31118917, 2019). "This is consistent with previous studies using monoclonal anti-HMGB1 2G7 antibody in experimental rodent models of stroke and lupus nephritis where minimal efficacy was observed." (PMID 30782181, 2019). "Then, the correlation between levels of HMGB1 and the number of immune cells in the blood after stroke was investigated." (PMID 31001089, 2019). "MyD88, a downstream effector molecule of TLR signaling has been shown to be involved in HMGB1-mediated post-ischemic inflammatory response and enhances stroke lesions when compared to MyD88 knockout mice in fMCAO model." (PMID 31291966, 2019). "In line with this idea, a number of reports have shown that HMGB-1 blockage reduces inflammation and improves behavioral recovery in experimental stroke." (PMID 31507379, 2019). "HMGB1 increases inflammation and necrosis in the acute phase after stroke, but promotes neurogenesis and angiogenesis in the delayed phase after stroke." (PMID 31123914, 2019). "The results revealed that HMGB1 levels were elevated in both stroke patients and rats after tPA treatment." (PMID 30139371, 2018). "The astrocytic HMGB1/IL-6 signaling pathway participates in angiogenesis, neurogenesis, and the promotion of post-stroke functional recovery." (PMID 30197589, 2018). "According to the results, the higher the extracellular HMGB1 levels in the serum and CSF, the larger the infarction volumes, demonstrating a correlation between levels of extracellular HMGB1 and stroke severity in the rat MCAO model." (PMID 29555931, 2018). "Considering ischemic injury itself can also induce HMGB1 release, to eliminate the possibility that timely accumulated HMGB1 release after ischemia leads to HMGB1 elevation, we compared its dynamic change in stroke rats with saline injection." (PMID 30139371, 2018). "In conclusion, the levels of serum HMGB1 seemed increased after thrombolysis in stroke patients and animals." (PMID 30139371, 2018). "Some investigations have demonstrated that serum/plasma HMGB1 concentrations are elevated in patients with strokes, acute myocardial infarction, and rheumatic arthritis." (PMID 30539006, 2018). "Many inflammatory conditions, such as aseptic trauma, acute lung injury, arthritis and stroke engage the innate immune response through the passive release of HMGB1 after cell lysis at sites of tissue damage." (PMID 29786644, 2018). "The reactive astrocytes in the peri-infarct cortex upregulated HMGB1 which stimulated the migration of endogenous endothelial progenitor cells to promote neurovascular remodeling during stroke recovery." (PMID 29615103, 2018).